INS (insulin)
Diseases named in the same sentence as INS in open-access papers (continued):
Sharing a sentence is not in itself a finding about the gene and the disease.
Obesity (continued). "It is known that SP is an important factor in obesity development, and there are several reports on the potential role of SP in insulin signaling dysregulation." (PMID 38612572, 2024). "The obesity paradox is also attributable to increased cardiac lipid supply from adipose lipolysis in the fasting cycle due to systemic insulin resistance and adiposity." (PMID 38544691, 2024). "Here, the variables obesity, waist circumference, MetS, AF, CVD, polyneuropathy, DFS, and insulin were associated with a lower HRQL." (PMID 39289410, 2024). "Bile acids can improve insulin sensitivity and reduce fat accumulation, thereby decreasing the occurrence of obesity, T2D, and NAFLD." (PMID 39850557, 2024). "Regular exercise is widely recognized for its beneficial effects on metabolic health, particularly in addressing obesity and enhancing insulin sensitivity." (PMID 38920999, 2024). "Higher MVPA and less ST potentially improved insulin sensitivity and reduced insulin secretion in 9-year-old children with overweight and obesity followed-up for 7 years, until late adolescence." (PMID 38441224, 2024). "In flies, diet-induced obesity produces many of the same pathophysiological effects observed in humans with obesity, indeed including hyperglycemia, altered insulin secretion, and insulin resistance." (PMID 39033139, 2024). "The purpose of this investigation was to determine the effects of resveratrol treatment on insulin action in skeletal muscle cells derived from lean individuals and individuals with severe obesity." (PMID 38324260, 2024). "Compared to patients with MODY 2, who were well-matched for hyperglycemia and obesity, patients with T1D were significantly more insulin resistant, suggesting that IR is driven by peripheral hyperinsulinemia and not hyperglycemia." (PMID 39906033, 2024). "The ongoing global pandemic of obesity and one of its key complications, T2D, highlight the importance of understanding all pathways regulating glucose and insulin signaling." (PMID 38199575, 2024). "In patients with MOD (Cluster 4), the identified etiological dysfunction was an obesity-driven peripheral resistance to insulin." (PMID 38805513, 2024). "Both TNFα and Il-1β were found to be able to influence insulin signaling, although it was also shown that circulating level of TNFα is lower than the effective concentration even in patients with obesity." (PMID 39004641, 2024). "Supplementation with glutamine has been shown to forestall the onset of insulin resistance by mitigating inflammation and fostering insulin sensitivity in skeletal muscle, as evidenced in a mouse model of obesity." (PMID 38732510, 2024). "The insulin fold change was lower in participants with obesity compared to overweight participants (p=0.042)." (PMID 38490484, 2024). "Weight cycling animals overall are not protected from metabolic complications of obesity compared to always having obesity animals and develop more extreme hyperinsulinemia and hypersecretion of insulin compared to age-matched controls." (PMID 38961153, 2024). "IR is defined as the loss of the ability of target tissues to respond to insulin signals, resulting in hyperinsulinemia and associated with many metabolic disorders in MDS, such as obesity, MASLD and hypertension." (PMID 39353925, 2024). "An expanding corpus of research has been dedicated to exploring the capacity of FMT to enhance insulin sensitivity in individuals afflicted with obesity and metabolic syndrome." (PMID 38792681, 2024). "Here, we investigated the effect of sucrose-free soybean oil-and fish oil-based high fat diets (HFDs) (SF-Soy-HFD and SF-Fish-HFD, respectively) on gut dysbiosis, obesity, steatosis, hepatic inflammation, and insulin resistance." (PMID 39165573, 2024). "GAL3, a lectin mainly secreted by macrophages, promotes inflammation and insulin insensitivity in obesity." (PMID 38201988, 2024).
Obesity (continued). "While the “obesity paradox” was initially observed, it became much less pronounced after accounting for insulin treatment and completely disappeared in patients with poorly controlled glycemia (HbA1C percentage > 7.5%)." (PMID 39125352, 2024). "Existing research shows that adipogenesis is a beneficial mechanism for combating obesity, a notion reinforced by our previous findings highlighting its correlation with enhanced insulin sensitivity and glucose homeostasis." (PMID 38672517, 2024). "So far, fetal insulin has received attention in pregnancies characterized by maternal diabetes or obesity as major contributor to excessive fat accretion." (PMID 38180040, 2024). "Kv1.3-KO mice exhibit higher metabolic rates, improved insulin sensitivity, and resistance to diet-induced obesity." (PMID 39605858, 2024). "Obesity increases insulin and adipocytokines levels and impairs baroreceptors’ sensitivity, enhancing the sympathetic nervous system’s activity." (PMID 38256505, 2024). "There is growing clinical evidence indicating that long-term dietary L-Arg supplementation can reduce the onset of T2DM by improving insulin secretion and sensitivity, as well as reducing obesity and hyperglycemia, as seen in our animals fed with L-Arg daily." (PMID 38426801, 2024). "Its molecular mechanisms contribute to protective effects on glucose homeostasis by mitigating inflammatory processes, improving insulin sensitivity, enhancing endothelial function, and facilitating vasodilation in obesity and diabetic subjects." (PMID 39538244, 2024). "In the current study, we further investigated the effects of GHSR on insulin secretion in male mice under diet-induced obesity (DIO) and streptozotocin (STZ)-induced β-cell injury in aging." (PMID 38794702, 2024). "These metabolites, including butyrate, play pivotal roles in maintaining intestinal barrier integrity, regulating immune responses, and influencing systemic health outcomes such as obesity and insulin sensitivity." (PMID 38585653, 2024). "Since the full-isoform of adipolin mediates insulin-sensitization and glucose uptake in the adipocytes, obesity-induced increased furin levels reduce insulin sensitivity and glucose uptake." (PMID 39308032, 2024). "Under insulin-resistant conditions, e.g., in individuals with obesity, pregnancy, or during puberty, insulin sensitivity would be reduced." (PMID 38299589, 2024). "Accumulating evidence suggests that it plays an important protective role in lipid and carbohydrate metabolism in an insulin-independent manner and in maintaining energy homeostasis, with anti-obesity, anti-diabetic, and anti-hyperlipidemic effects." (PMID 39409124, 2024). "Obesity induced a significant increase in plasma insulin levels that was reverted by all of the interventions assayed, reaching values that were even lower than those reported for the SD group." (PMID 38539808, 2024). "Obesity results in dysregulation of energy homeostasis, insulin sensitivity, glucose uptake, and inflammation." (PMID 39596898, 2024). "Blood insulin levels in obese males were many times higher than in control males, irrespective of the age at which the diet was started and the degree of obesity, but hyperglycaemia only developed in 17CafD males." (PMID 39596499, 2024). "Combined exercise training and genistein mitigated the unwanted effects of obesity on insulin action and glucose homeostasis, hepatic gluconeogenesis, hepatic injury, and steatosis." (PMID 39201705, 2024). "Nonetheless, more studies are needed in the future to examine its association with obesity, the underlying mechanisms, and other related factors, including studies on the liver, adipose tissues, and responses to insulin and glucose in animal models of obesity." (PMID 38947126, 2024).
Obesity (continued). "Deficiency of the endoplasmic reticulum stress response T-cell death–associated gene 51 (TDAG51) (TDAG51−/−) in mice promotes the development of high-fat diet (HFD)-induced obesity, fatty liver, and hepatic insulin resistance." (PMID 38237682, 2024). "Lifestyle interventions targeting PA and nutrition have proven to be effective in the short-term to lower IMF and improve insulin sensitivity in patients with T2D or with obesity." (PMID 38732623, 2024). "In summary, these studies show that both sex and obesity influence insulin regulation of adipose tissue lipolysis in a depot-specific fashion." (PMID 38602778, 2024). "In this study, we investigated the relationship between body composition and body fat distribution and whole-body and tissue-specific insulin sensitivity in men and women with overweight and obesity using state-of-the-art whole-body MRI technology." (PMID 38594756, 2024). "The high prevalence of obesity in our cohort also support involvement of augmented beta cell activity to counter insulin sensitivity but requires further investigations to confirm." (PMID 38938516, 2024). "IR-related features include overweight/obesity/central obesity, hypertension, atherogenic dyslipidemia, and decreased estimated insulin sensitivity (eIS)." (PMID 38212850, 2024). "Senotherapeutics have been shown to reduce senescent cell burden in diet-induced obesity, to alleviate metabolic dysfunction, and to restore the capacity of preadipocytes to differentiate into functional insulin-responsive fat cells." (PMID 38812556, 2024). "RJ has demonstrated efficacy in regulating body composition, mitigating muscle lipotoxicity, enhancing insulin sensitivity, and reducing adipose tissue mass and body weight in both human and animal models of obesity." (PMID 39339774, 2024). "Macrophages residing in lean AT tissues exhibit characteristics of anti-inflammatory M2-like macrophages and have a positive role in maintaining AT homeostasis, preventing obesity-induced inflammation and thus promoting insulin sensitivity." (PMID 38533504, 2024). "First, in animal models of diet-induced obesity, Withaferin A supplementation reduced hepatic fat, restored hepatic insulin sensitivity, and increased superoxide dismutase (SOD), catalase (CAT), glutathione peroxidase (GPx), and GSH content in the liver." (PMID 39064738, 2024). "When L-theanine was administered to high-fat diet-fed mice, it resulted in increased energy expenditure, reduced obesity, and improved glucose tolerance and insulin sensitivity." (PMID 39351529, 2024). "This confirms that there is an anabolic state in obesity, a condition that is driven by insulin, a hormone that is secreted in a greater proportion than glucagon even in a fasting state." (PMID 38665134, 2024). "Amylin, a pancreatic hormone that is cosecreted with insulin, has been highlighted as a potential treatment target for obesity." (PMID 38806231, 2024). "Many studies have shown that Bifidobacterium intervention can improve HFD-induced obesity, as well as the inflammation and insulin resistance." (PMID 39425211, 2024). "Collectively, these miRNAs form a complex network regulating insulin sensitivity and inflammation in obesity." (PMID 39337290, 2024). "Overall, the evidence above indicates the strong potential of RSV administration to exert anti-obesity effects, increase insulin sensitivity, and improve glucose tolerance in animal models of obesity and insulin resistance." (PMID 39598748, 2024). "Five studies, with a total of 75 participants (44 men / 31 women, 48 with obesity, 27 with T2D), were included in the meta-analysis on fasting insulin and aerobic exercise." (PMID 39467940, 2024). "Together, our findings establish miR-6236 as an ATM-secreted miRNA that potentiates adipocyte insulin signaling and protects against metabolic dysfunction during obesity." (PMID 38918428, 2024).
Obesity (continued). "Periods of low osteoglycin, seen in obesity, reduce food intake and insulin sensitivity, thus increasing serum glucose availability." (PMID 39588310, 2024). "With the exception of adiponectin, obesity-related biomarkers including glucose, insulin, triglycerides, cholesterol, and leptin were significantly aggravated in human APOE expressing mice compared to unmodified C57BL/6J mice." (PMID 37450924, 2024). "In this study, we examined the effects of obesity on insulin-stimulated intestinal GU from blood (small intestine and colon) and microbiota composition in monozygotic twins discordant for body mass index (BMI)." (PMID 39458548, 2024). "Reducing insulinemia and plasma total cholesterol and improving insulin sensitivity in patients with obesity-related metabolic disorders." (PMID 38283696, 2024). "Three studies evaluated the effects of seaweed-derived SPs on obesity-related hormones, namely insulin, in comparison to an untreated group." (PMID 39728103, 2024). "We observed generally similar association patterns within the two gene sets, with phenotypes related to insulin sensitivity and obesity (HOMAIR, Matsuda index, fasting insulin) ranking among the highest for the numbers of DE genes in both gene sets." (PMID 38297378, 2024). "These factors include poor glycemic control, obesity, IR, dyslipidemia, lipoprotein abnormalities, poor dietary habits, impaired systemic to portal insulin gradient, and altered gut microbiome in genetically susceptible individuals." (PMID 39605938, 2024). "Alterations in SCFA production due to obesity can impact insulin sensitivity and glucose regulation." (PMID 39104999, 2024). "Because it metabolizes the production of heat by burning fat and controls glucose homeostasis and insulin levels, this fat is considered an effective target for anti-obesity treatment." (PMID 39125449, 2024). "Our data indicate that miR-6236 acts as a regulator of adipose tissue insulin signaling and systemic glucose homeostasis during obesity." (PMID 38918428, 2024). "This study indicates that obesity impairs insulin-stimulated intestinal GU (intestinal uptake of circulating glucose from blood) independent of genetics." (PMID 39458548, 2024). "This feedback loop between liver dysfunction and systemic metabolic disturbances perpetuates and worsens hepatic insulin resistance, creating a vicious cycle of metabolic dysregulation that is central to the pathology of obesity-related liver diseases." (PMID 39000518, 2024). "Numerous animal models are used for NAFLD investigation, and the best model should include all metabolic abnormalities, serum lipid profile alteration, insulin resistance, liver fat accumulation, and obesity." (PMID 39000518, 2024). "The high heterogeneity of the results likely responds to different baseline A1c, variable rates of obesity, as well as different titration protocols to adjust insulin doses." (PMID 39906033, 2024). "According to the Carbohydrate-Insulin Model (CIM) of obesity, a high-carbohydrate diet including refined grains and sugar intake produces a similar postprandial hyperinsulinaemia." (PMID 38799425, 2024). "Mice with osteoblasts overexpressing OCN experienced hypoglycemia and were protected against obesity and poor glucose tolerance due to increased pancreatic β cell proliferation, insulin secretion, and insulin sensitivity." (PMID 38945950, 2024). "In young patients affected by PCOS, metformin remains the most effective and cost-efficient therapy to regulate insulin sensitivity in the condition of overweight and/or obesity." (PMID 39337980, 2024). "In line with this, rs7607980 is related to lower fasting insulin in children with overweight and obesity." (PMID 38674416, 2024). "SIRT1 plays multifaceted roles in obesity including the regulation of inflammation by inhibiting nuclear factor κ-B (NF-κB), thereby reducing inflammatory responses and improving insulin sensitivity." (PMID 39707172, 2024).
Obesity (continued). "Reducing energy intake and exercising are often considered essential components for treating obesity and insulin dysregulation." (PMID 38886475, 2024). "In a small study, patients with obesity and PCOs who underwent KD for 24 weeks, had significant reductions in body weight (−12%), fasting insulin (−54%), percent free testosterone (−22%), and LH/FSH ratio (−36%)." (PMID 39328462, 2024). "Here, the authors show that Mir6236 is secreted by adipose tissue macrophages and regulates adipocyte insulin resistance and organismal metabolism during obesity." (PMID 38918428, 2024). "Higher levels of adiponectin, despite being lower in patients with obesity, can improve insulin sensitivity and exert anti-inflammatory properties, potentially offsetting some negative health outcomes associated with obesity." (PMID 39402270, 2024). "One study showed that liraglutide, a GLP-1 receptor agonist approved for human T2D and obesity, improved glycemic control during hyperglycemia in healthy cats by increasing insulin concentrations and decreasing glucagon concentrations." (PMID 38785817, 2024). "Bacteroides, Phascolarctobacterium, Dialister, and Veillonella's principal metabolite is propionic acid, which can control the levels of insulin and blood sugar to prevent diet‐induced obesity." (PMID 39619999, 2024). "HFD led to substantial obesity, hyperglycemia, and impaired insulin sensitivity in both Nrf2+/− and Nrf2+/+ mice." (PMID 38612986, 2024). "In a sample of adolescents with obesity, a biphasic glucose response was associated with the highest insulin sensitivity and lowest area under an OGTT insulin curve." (PMID 38576510, 2024). "Hedgehog signaling activation prevents high-fat diet-induced obesity, improves systemic glucose tolerance, and increases insulin sensitivity." (PMID 38292473, 2024). "Insulin secretion from pancreatic β cells is a key pillar of glucose homeostasis, which is impaired under obesity and aging." (PMID 38794702, 2024). "For more than 30 years sympathetic nervous system (SNS) and kidney sodium reabsorption activation, secondary to insulin resistance and compensatory hyperinsulinemia, have been considered as primary mediators of elevated BP in obesity." (PMID 38186879, 2024). "Dysosmobacter welbionis, a newly discovered gut probiotic, can effectively alleviate obesity, insulin resistance, and inflammation in adipose tissue, thereby improving host metabolic status." (PMID 38375198, 2024). "T2DM, characterized by hyperglycemia and obesity, is a chronic metabolism disease due to insufficient insulin production or insulin resistance in the pancreas." (PMID 38509482, 2024). "A previous study reported associations between genetic variations in nuclear genes related to mitochondrial function and body mass index, waist-to-hip ratio, extreme obesity, blood glucose, insulin, and glycated hemoglobin levels." (PMID 38862964, 2024). "Among these, Muribaculaceae increased insulin sensitivity, reduce host obesity by producing SCFA, promoted fat decomposition and fatty acid oxidation, and inhibited cholesterol synthesis in the liver." (PMID 38500527, 2024). "ALA also enhances insulin sensitivity and shows the potential in preventing microvascular complications and ameliorating comorbidities like obesity, hypertension, and dyslipidemia." (PMID 39598447, 2024). "Loss of Fabp5 gene expression leads to increased systemic insulin sensitivity in animal models of obesity and IR, and adipocytes isolated from Fabp5 -/- mice also exhibit increased insulin-stimulated glucose transport capacity." (PMID 39075482, 2024). "Cholesterol imbalance is a feature of enlarged fat cells in obese states, and cholesterol normalization is beneficial in reversing insulin resistance and combating the development of obesity." (PMID 38685082, 2024). "Pregnant women with obesity present higher levels of free fatty acids and glucose, reduction in insulin sensitivity, and adipose tissue endocrine dysregulation." (PMID 39083072, 2024).